POPDC2 (popeye domain cAMP effector 2)
Description:
Important for the maintenance of cardiac function. Plays a regulatory function in heart rate dynamics mediated, at least in part, through cAMP-binding and, probably, by increasing cell surface expression of the potassium channel KCNK2 and enhancing current density.
Synonyms: POP2; CCCM2
Tractability: Antibody: UniProt places it where antibodies can reach, with high confidence; its Gene Ontology location is reachable by antibodies, with high confidence; UniProt predicts a signal peptide or a membrane-spanning region.
Gene: Protein-coding gene on chromosome 3 (119,636,457 to 119,665,324, reverse strand). Ensembl gene ENSG00000121577.
Subcellular location: Membrane; Cell membrane, sarcolemma
Gene Ontology:
Molecular function: cAMP binding
Biological process: regulation of heart rate; heart development; regulation of membrane potential; skeletal muscle tissue development; striated muscle cell differentiation
Cellular component: membrane; sarcolemma
Genetic constraint (gnomAD): Loss-of-function variants: 21 observed, 28.64 expected, observed/expected ratio (o/e) 0.73, 90% interval 0.52 to 1.06. The upper end of that interval is the gene's LOEUF score, 1.06, which puts it in group 4 of 6, group 1 being the genes least tolerant of losing a copy. Missense variants: 405 observed, 465.37 expected, observed/expected ratio (o/e) 0.87, 90% interval 0.8 to 0.94. Synonymous variants: 184 observed, 191.21 expected, observed/expected ratio (o/e) 0.96, 90% interval 0.85 to 1.09.
Homologues: Orthologues: chimpanzee POPDC2 (99% identical), macaque POPDC2 (89% identical), pig POPDC2 (84% identical), rat Popdc2 (84% identical), mouse Popdc2 (84% identical), guinea pig POPDC2 (83% identical), rabbit POPDC2 (80% identical), dog POPDC2 (79% identical), tropical clawed frog popdc2 (54% identical), zebrafish popdc2 (51% identical), Drosophila melanogaster bves (24% identical). Paralogues in human: POPDC3 (37% identical), POPDC1 (25% identical).
Diseases named in the same sentence as POPDC2 in open-access papers:
POPDC2 is named in the same sentence as 22 diseases in open-access papers, as found by Europe PMC text mining. Sharing a sentence is not in itself a finding about the gene and the disease. The quoted sentences say what the papers report.
cardiac arrhythmia (10 papers, 2017 to 2025). Any disturbances of the normal rhythmic beating of the heart or MYOCARDIAL CONTRACTION. "Patients carrying POPDC2 variants show only cardiac arrhythmias, while POPDC3 variants are only associated with LGMD." (PMID 36624536, 2023). "Mutations in blood vessel epicardial substance (BVES) also known as POPDC1 and POPDC2 have been associated with limb-girdle muscular dystrophy and cardiac arrhythmia." (PMID 36624536, 2023). "Mice with null mutations in POPDC2 develop muscle dystrophy and cardiac arrhythmia." (PMID 31783652, 2019). "Mutations in human POPDC1, POPDC2 and in human XIRP1, all cause pathological cardiac arrhythmias, suggesting a possible role for POPDC1/2 and XIRP1 interaction in normal cardiac conduction." (PMID 33261556, 2020). "Consistent with its predominant expression in striated muscle, Popdc1 and Popdc2 null mutants in mouse and zebrafish develop cardiac arrhythmia and muscular dystrophy." (PMID 31197601, 2019). "Popdc2, one of the Popeye domain-containing (Popdc) gene families, was highly expressed particularly in the sinoatrial node of the mouse and represented as a novel arrhythmia gene for cardiac conduction disorders." (PMID 37355664, 2023). "Mutations found in POPDC2 cause patients to develop a cardiac arrhythmia phenotype but importantly do not display any skeletal muscle phenotype." (PMID 34940515, 2021).
Sinus bradycardia (6 papers, 2016 to 2025). Bradycardia related to a mean resting sinus rate of less than 50 beats per minute. "The cardiac-specific knockout of Kcnk2, which encodes TREK-1, produces a stress-induced sinus bradycardia with a phenotypical manifestation that largely resembles the one described for Popdc1 and Popdc2 null mutants." (PMID 34940515, 2021). "The cardiac arrest accompanied by sinus bradycardia and first-degree AV block he displayed fitted the conduction disease seen in the other POPDC2-affected individuals." (PMID 40409267, 2025). "Popdc1 and Popdc2 are highly expressed in the SAN and loss of function mutations in mice are causing a stress-induced sinus bradycardia phenotype 13." (PMID 34999055, 2022). "A cardiac specific knockout of Kcnk2, which encodes TREK-1, displays a stress-induced sinus bradycardia similar to the one observed in Popdc1 and Popdc2 null mutants, suggesting that the sinus bradycardia in POPDC mutants may in part be due to an impaired TREK-1 current." (PMID 28939104, 2017). "In contrast, Popdc1 and Popdc2 null mutants have a stress-induced sinus bradycardia, while an AV-block has not yet been described." (PMID 27347491, 2016).
Bradycardia (4 papers, 2014 to 2025). A slower than normal heart rate (in adults, slower than 60 beats per minute). "In an effort to shed light on the electrophysiological mechanism by which the variants in POPDC2 lead to bradycardia, we therefore conducted co-expression studies of WT and mutant POPDC2 with TREK-1." (PMID 40409267, 2025). "Furthermore, cardiac-specific TREK-1-deficient mice display a sinus node phenotype characterized by bradycardia with frequent episodes of sinus pauses, partially resembling the phenotype in the affected individuals with bi-allelic POPDC2 variants presented here." (PMID 40409267, 2025). "Both POPDC1 and PDE4 are highly expressed in the SAN and Popdc1 and Popdc2 KO mice display a stress-induced sinus bradycardia." (PMID 34999055, 2022). "Mutant mice with a deletion of either Popdc1 or Popdc2 exhibit severe stress‐induced bradycardia with high HR variability and long sinus pauses." (PMID 36254885, 2022). "Interestingly, the cardiac phenotype, which is present in both, Popdc1 and Popdc2 null mutants, is characterized by a stress-induced sinus bradycardia, suggesting that Popdc proteins participate in cAMP signaling in the sinuatrial node." (PMID 27500161, 2014). "Given that deletion or mutation of POPDC1 often leads to loss of POPDC2 membrane localization, and deletion of either POPDC isoform closely phenocopies one another with respect to HR variability and stress‐induced bradycardia, POPDC1 likely heterodimerizes with POPDC2." (PMID 36254885, 2022). "In vitro, both POPDC2 variants tested failed to increase TREK-1 current and, by virtue of observations of bradycardia in TREK-1-deficient mice, these variants would be expected to be associated with bradycardia." (PMID 40409267, 2025).
muscular dystrophy (4 papers, 2019 to 2025). Muscular dystrophy (MD) refers to a group of more than 30 genetic diseases characterized by progressive weakness and degeneration of the skeletal muscles that control movement. "We then conducted genetic burden analyses, wherein rare variants in POPDC2 are aggregated, with the phenotypes above and muscular dystrophy as this is a clinical hallmark of recessive syndromes associated with the two other members of the POPDC family (i.e., POPDC1 and POPDC3)." (PMID 40409267, 2025). "Indeed, POPDC2 is predominantly expressed in cardiac tissue, whereas POPDC3, which presents with isolated muscular dystrophy, has a predominant expression in skeletal muscle." (PMID 40409267, 2025).
AV block (3 papers, 2021 to 2025). "Bi-allelic variants in POPDC2 cause a recessive syndrome characterized by sinus node dysfunction, AV block, and hypertrophic cardiomyopathy." (PMID 40409267, 2025). "The mutations disrupting the regulation of TREK-1 by POPDC1 or POPDC2 proteins lead to the development of familial AV block." (PMID 34445768, 2021). "Furthermore, POPDC1 and POPDC2 double knockout animals exhibited signs of atrioventricular conduction disorder (AV block)." (PMID 34445768, 2021).
limb-girdle muscular dystrophy (2 papers, 2022 to 2023). Limb-girdle muscular dystrophy (LGMD) is a heterogeneous group of muscular dystrophies characterized by proximal weakness affecting the pelvic and shoulder girdles. "Mutations in POPDC1, POPDC2 and POPDC3 have been recently identified in patients suffering from cardiac arrhythmia and/or limb-girdle muscular dystrophy, respectively." (PMID 34999055, 2022). "Although it is currently not known whether POPDC2 and POPDC3 also bind PDE4, mutation of leucine 155 to histidine in POPDC3, which corresponds to leucine 173 in POPDC1, was recently identified in a patient suffering from limb-girdle muscular dystrophy (LGMDR26, OMIM 605824)." (PMID 34999055, 2022).
breast carcinoma (1 paper, 2019). "Enhanced expression of POPDC2 was observed at all clinical stages of breast cancer while POPDC3 was only expressed at higher levels in early stages of the disease." (PMID 31817925, 2019). "In a recent study that examined the expression of POPDC proteins in ductal breast carcinoma, POPDC2 and POPDC3 were found to be significantly overexpressed in breast cancer tissues." (PMID 31817925, 2019). "Overall, this data suggests potential oncogenic roles of POPDC2 and POPDC3 in breast cancer with POPDC3 potentially only involved in initiating breast tumorigenesis, while POPDC2 seems to be involved in initiating and sustaining breast cancer at all clinical stages." (PMID 31817925, 2019).
cardiac hypertrophy (1 paper, 2025). "One of the potential mechanisms underlying cardiac hypertrophy in affected individuals with recessive variants in POPDC2 is modulation of TREK-1." (PMID 40409267, 2025).
cardiomyopathy (1 paper, 2013). A disease of the heart muscle or myocardium proper. "For example, the presence of congenital heart disease could possibly be ascribed to the deregulation of the DES, LDB3, POPDC2 and SLC4A3 genes, all of which have previously been associated with cardiac function and pathology, such as cardiomyopathy." (PMID 23816241, 2013).
hepatocellular carcinoma (1 paper, 2025). A malignant tumor that arises from hepatocytes. "Bioinformatics insights unveiled FR036820 and FR121302 as crucial en‐lncRNAs in hepatocellular carcinoma, modulating the adjacent genes Ttc22 and Popdc2, respectively." (PMID 40661810, 2025). "Furthermore, a stable FR121302‐shRNA and overexpressing tumor cell line confirmed FR121302's role as an enhancer RNA, regulating Popdc2 expression in hepatocellular carcinoma." (PMID 40661810, 2025).
hypertrophic cardiomyopathy (1 paper, 2025). A condition in which the myocardium is hypertrophied without an obvious cause. "We identified bi-allelic variants in POPDC2 in four families with a phenotypic spectrum consisting of sinus node dysfunction, AV conduction defects, and hypertrophic cardiomyopathy." (PMID 40409267, 2025). "Here, we provide evidence for bi-allelic loss-of-function (LOF) variants in POPDC2 as the cause of an autosomal recessive syndrome in four families, consisting of a phenotypic spectrum including sinus node disease and AV conduction defects with hypertrophic cardiomyopathy (HCM; MIM: 192600)." (PMID 40409267, 2025).
myocarditis (1 paper, 2025). Myocarditis is a condition that is characterized by inflammation of the heart muscle (myocardium). "The question remains whether the myocarditis exposed the underlying POPDC2-related conduction disease or whether myocarditis is part of the POPDC2 phenotypic spectrum." (PMID 40409267, 2025). "While we find it unlikely, compound heterozygosity of the truncating POPDC2 variants might have been irrelevant in this case, and the phenotype could be fully the consequence of myocarditis." (PMID 40409267, 2025).
prostate carcinoma (1 paper, 2022). A carcinoma that arises from epithelial cells of the prostate gland. "POPDC2 was found to be present in cancer tissue sequences, such as prostate cancer." (PMID 34541834, 2022).
sick sinus syndrome (1 paper, 2021). A constellation of signs and symptoms which may include syncope, fatigue, dizziness, and alternating periods of bradycardia and atrial tachycardia, which is caused by sinoatrial node dysfunction. "SAN dysfunction in Popdc1 and Popdc2 null mutants is reminiscent of sick sinus syndrome (SSS) in patients." (PMID 34940515, 2021).
cancer (2 papers, 2019 to 2022). A tumor composed of atypical neoplastic, often pleomorphic cells that invade other tissues. "In contrast to POPDC1, POPDC2 and POPDC3, have been associated with both oncogenic and tumor suppressor roles in different cancer types suggesting that these proteins might serve tissue-specific functions." (PMID 31817925, 2019). "This suggests that the roles of POPDC2 and POPDC3 might differ in different cancers while POPDC1 potentially regulates cell proliferation in a similar manner in different tissues." (PMID 31817925, 2019). "Investigating the roles and mechanisms by which POPDC2 and POPDC3 potentially regulate migration, invasion and metastasis will also provide the much-needed clarity on how diverse the functions of POPDC proteins might be in various cancer types." (PMID 31817925, 2019).
tumor (1 paper, 2025). "Analysis of fresh tumor tissue lysates revealed the mRNA levels of POPDC1 and POPDC2 remained unchanged, but there was a substantial upregulation in POPDC3 mRNA and protein levels in POPDC3-OE priNSCLC-1 xenografts." (PMID 39971925, 2025). "Analysis of fresh tumor tissue lysates revealed substantial reductions in POPDC3 mRNA and protein levels in sh-POPDC3 xenografts, while the mRNA levels of POPDC1 and POPDC2 remained unchanged." (PMID 39971925, 2025).
POPDC2 also shares sentences with these, for which no sentence is quoted: Arrhythmia (1 paper); cardiac arrest (1); cardiac conduction defect (1); cardiac conduction disease (1); congenital heart disease (1); leiomyoma (1).